SGSM1 (small G protein signaling modulator 1)
Description:
Interacts with numerous Rab family members, functioning as Rab effector for some, and as GTPase activator for others. Promotes GTP hydrolysis by RAB34 and RAB36. Probably functions as a GTPase effector with RAB9A and RAB9B; does not stimulate GTP hydrolysis with RAB9A and RAB9B.
Synonyms: KIAA1941; RUTBC2
Tractability: Antibody: UniProt places it where antibodies can reach, with high confidence. PROTAC: its protein half-life has been measured.
Gene: Protein-coding gene on chromosome 22 (24,806,169 to 24,927,578, forward strand). Ensembl gene ENSG00000167037.
Subcellular location: Golgi apparatus, trans-Golgi network; Cytoplasmic vesicle membrane; Cytoplasm
Gene Ontology:
Molecular function: GTPase activator activity; protein binding; small GTPase binding
Cellular component: cytoplasm; cytoplasmic vesicle membrane; cytosol; cytoplasmic vesicle; Golgi apparatus
Genetic constraint (gnomAD): Loss-of-function variants: 72 observed, 130.18 expected, observed/expected ratio (o/e) 0.55, 90% interval 0.46 to 0.67. The upper end of that interval is the gene's LOEUF score, 0.67, which puts it in group 2 of 6, group 1 being the genes least tolerant of losing a copy. Missense variants: 1,207 observed, 1,483.9 expected, observed/expected ratio (o/e) 0.81, 90% interval 0.77 to 0.85. Synonymous variants: 558 observed, 584.61 expected, observed/expected ratio (o/e) 0.95, 90% interval 0.89 to 1.02.
Homologues: Orthologues: macaque SGSM1 (99% identical), chimpanzee SGSM1 (97% identical), pig SGSM1 (96% identical), guinea pig SGSM1 (95% identical), rat Sgsm1 (94% identical), mouse Sgsm1 (94% identical), dog SGSM1 (94% identical), rabbit SGSM1 (89% identical), tropical clawed frog sgsm1 (82% identical), zebrafish sgsm1a (72% identical), zebrafish sgsm1b (70% identical). Paralogues in human: SGSM2 (58% identical), TBC1D9B (11% identical), TBC1D9 (11% identical), TBC1D30 (11% identical), TBC1D8 (10% identical), EVI5L (10% identical), TBC1D8B (9% identical), EVI5 (9% identical), TBC1D2B (8% identical), TBC1D2 (8% identical), TBC1D4 (8% identical), TBCK (8% identical), and 33 more.
Diseases named in the same sentence as SGSM1 in open-access papers:
SGSM1 is named in the same sentence as 11 diseases in open-access papers, as found by Europe PMC text mining. Sharing a sentence is not in itself a finding about the gene and the disease. The quoted sentences say what the papers report.
glioma (3 papers, 2022 to 2024). A benign or malignant brain and spinal cord tumor that arises from glial cells (astrocytes, oligodendrocytes, ependymal cells). "The downregulation of SGSM1 expression was found to be associated with poor survival time in patients with either low-grade glioma or its subtypes." (PMID 38460946, 2024). "Furthermore, the expression of small G protein signaling modulator 1 (SGSM1) tended to be relatively diminished in low-grade glioma tissues." (PMID 38460946, 2024). "Small G Protein Signaling Modulator 1 (SGSM1) has hardly been studied in gliomas." (PMID 35484511, 2022).
autosomal dominant adult-onset proximal spinal muscular atrophy (1 paper, 2022). "Diseases associated with SGSM1 include autosomal dominant adult-onset proximal spinal muscular atrophy and spinal muscular atrophy, with lower extremity predominance." (PMID 35448080, 2022).
Obesity (1 paper, 2023). Accumulation of substantial excess body fat. "Our data also revealed that a duplication in the first intron of the SGMS1 (Small G Protein Signaling Modulator 1) gene may lead to reduced body weight and a lower risk of obesity." (PMID 37799139, 2023).
cancer (3 papers, 2021 to 2025). A tumor composed of atypical neoplastic, often pleomorphic cells that invade other tissues. "Comparing SGSM1 expression between normal tissues and tumor samples from TCGA and GTEx databases, we found that SGSM1 was significantly down-regulated in most types of cancer, including LGG (P < 0.001)." (PMID 35484511, 2022). "Among the 54 cancer-related genes, DGKG, MPND, NPIPB5, PRR21, SGSM1, and TRIM67 displayed frameshift mutations." (PMID 34104084, 2021). "The expression of SGSM1 was significantly down-regulated in most types of cancer, including LGG." (PMID 35484511, 2022). "In addition, the present study revealed 6 cancer-related genes, DGKG, MPND, NPIPB5, PRR21, SGSM1, and TRIM67, which showed novel frameshift mutations." (PMID 34104084, 2021).
tumor (2 papers, 2019 to 2022). "SGSM1 potentially influenced tumor immunology, and could be a potential therapeutic target for immunotherapy rather than a simple prognostic biomarker." (PMID 35484511, 2022). "Increased infiltration of macrophages in low SGSM1 expression tumors suggested that immune microenvironment was driven from anti-tumor state to immunosuppressive state due to the phenotypic transformation of tumor-associated macrophages, indicated a higher risk of tumor invasion." (PMID 35484511, 2022).
neurological disorders (1 paper, 2024). "In mice (Mus musculus), mutations in the CYFIP2 and SGSM1 genes can influence many neurological disorders." (PMID 39829673, 2024).
SGSM1 also shares sentences with these, for which no sentence is quoted: Alzheimer disease (1 paper); astrocytoma (1); nasopharyngeal carcinoma (1); skin cutaneous melanoma (1); spinal muscular atrophy (1).